MICOS10-NBL1 (MICOS10-NBL1 readthrough)
Synonyms: formerly MINOS1-NBL1
Gene: Protein-coding gene on chromosome 1 (19,597,067 to 19,656,927, forward strand). Ensembl gene ENSG00000270136.
Genetic constraint (gnomAD): Missense variants: 37 observed, 28.76 expected, observed/expected ratio (o/e) 1.29, 90% interval 0.99 to 1.69. Synonymous variants: 13 observed, 11.81 expected, observed/expected ratio (o/e) 1.1, 90% interval 0.71 to 1.71.